STAT3 (signal transducer and activator of transcription 3)
Diseases named in the same sentence as STAT3 in open-access papers (continued):
Sharing a sentence is not in itself a finding about the gene and the disease.
neutropenia (continued). "Moreover, the 7 patients with STAT3 mutations have neutropenia and a CD56-/Vδ2- phenotype, and the 3 cases with STAT5B mutations display an asymptomatic clinical course and CD56/Vδ2 expression." (PMID 35676278, 2022). "In contrast, neutropenia and STAT3 mutations were almost exclusively found in CD8+ cases." (PMID 34359799, 2021). "Besides neutropenia, several other clinical features have been described to be more frequent in patients with STAT3 mutations, including different cytopenias or autoimmune diseases." (PMID 32133291, 2020). "Previous publications have shown that STAT3 mutations were associated with neutropenia, anemia, or both compared to STAT3 WT patients, but these were generally a heterogeneous mix of mutant samples rather than precise individual mutational groups as analyzed here." (PMID 32710512, 2020). "Thus, in general, a more clinically symptomatic disease is likely to be associated to the presence of STAT3 mutations and the evidence that neutropenia is more detectable in more severely affected patients suggests that STAT3 aberrancies might be responsible." (PMID 38238319, 2024). "Among these, the STAT3-miR146b-FasL axis has been shown to be paramount in the pathogenesis of neutropenia which is also a common feature to all other diseases accompanying/overlapping T-LGLL." (PMID 38238319, 2024). "In the NK-LGLL subtype, STAT3 mutations usually occur in LGL clones expressing CD16high/CD56dim/neg/CD57− and clinically manifest with severe neutropenia, whereas STAT5b mutations have rarely been detected." (PMID 36358655, 2022). "All the 7 Tγδ LGLL patients with STAT3 mutations were characterized by CD56− LGLs (P < 0.01) and symptomatic disease (100%, P < 0.05), mainly neutropenia." (PMID 35676278, 2022). "At a molecular level, a high incidence of STAT3 mutations has been observed in both T-LGLL and NK-LGLL patients with neutropenia." (PMID 36358655, 2022). "Of note, STAT3 activation was shown to drive FasL expression, further supporting a STAT3 pathogenetic role in neutropenia development." (PMID 34685780, 2021). "The recent identification of a STAT3-mediated miR-146b down-regulation in neutropenic T-LGLL patients emphasized the pathogenetic role of STAT3 activation in neutropenia development." (PMID 34685780, 2021). "To get insights into the molecular bases of neutropenia in these patients, we demonstrated a link between STAT3 phosphorylation and Fas ligand transcription levels." (PMID 28977911, 2017). "The evidence that CD8+/CD16+/CD56- patients were characterized by higher level of Fas ligand, as a consequence of their higher STAT3 phosphorylation, offers a mechanistic explanation for the correlation between STAT3 activation and neutropenia." (PMID 28977911, 2017). "Interestingly, somatic mutations of the SH2 domain of STAT3 were identified in the lymphoid compartment in patients with myelodysplastic syndrome and profound neutropenia, consistent with the presence of subclinical T-cell clones which may be involved in the development of hypocellularity." (PMID 24618699, 2014). "Our results demonstrate the remarkable correlation of STAT3 mutation with PRCA, neutropenia and ß2-MG." (PMID 24283217, 2013). "High ß2-MG (ß2-microglobulin) levels (P = 0.005), neutropenia (P = 0.018) and PRCA (P = 0.001) all displayed a significant association with STAT3 mutations." (PMID 24283217, 2013). "Patients with STAT3 mutations develop RA and neutropenia more often than patients without these mutations." (PMID 36117975, 2022). "We hypothesized that the mechanism accounting for neutropenia development involves high levels of STAT3 activation." (PMID 32133291, 2020). "Vbeta analysis was performed on the entire cohort of patients and no specific association was found between the presence of STAT3 mutations, neutropenia and Vbeta usage." (PMID 28977911, 2017).
neutropenia (continued). "According to our policy to treat patients when symptomatic for neutropenia and not according to neutrophils number, at the time of the study only 13 patients required treatment, 12 out of 13 were STAT3 mutated (92.3%; χ2 = 19.0, P < 0.0001)." (PMID 28977911, 2017). "Some literature data correlated the presence of STAT3 mutations with neutropenia, but these data were not confirmed by other authors, moreover this correlation was not yet specifically evaluated in comparable series of cases." (PMID 28977911, 2017). "However, the mice lacking STAT3 in hematopoietic cells exhibit granulocytosis instead of neutropenia, while the hematopoietic cells respond more strongly to G-CSF, indicating that STAT3 might play a negative regulatory role in neutrophil differentiation." (PMID 37507383, 2023). "These novel data, emphasizing the role of a STAT3/miR-146b/FasL axis, elucidated the molecular mechanism accounting for the increased s-FasL expression and, for the first time, showed the involvement of an miRNA in the pathogenesis of LGLL-associated neutropenia." (PMID 34685780, 2021). "Some authors reported that STAT3 genetic lesions are associated with neutropenia, although this correlation has not yet been specifically evaluated also in consideration that the pathogenesis of neutropenia is likely to be multifactorial, comprising both humoral and cytotoxic mechanisms." (PMID 28977911, 2017). "Overall, these data appear to explain the observations that individuals with neutropenia, defective TACI and/or an impaired STAT3 have reduced MZB cells and exhibit reduced IgA and IgG antibody production toward T-dependent antigens." (PMID 35682784, 2022). "Although data are still limited, up to now STAT3 mutations have not been detected in T-CUS and patients with STAT3 mutations develop RA and neutropenia more often than patients without these mutations." (PMID 38238319, 2024). "Since FasL is not a direct STAT3 target, a high throughput miRNome analysis was performed to investigate miRNA differentially expressed in patients characterized by neutropenia, as compared to those with normal ANC and healthy controls." (PMID 34685780, 2021). "While we didn’t detect a difference in the immunoreactivity of STAT3 at the level of the OVLT between immunocompetent and neutropenic mice, we did find indications that hypothalamic synthesis of PGE2 may be enhanced by neutropenia at 24 h p.i. using the precursors COX2 and mPGES." (PMID 40534875, 2025). "In this study, we stratified 81 patients with RA and unexplained neutropenia or/and an increase in the number of LGLs into two groups (RA-associated T-LGLL or FS) based on the presence or absence of T-cell clonality; we then examined STAT3 and STAT5b gene mutations in both groups." (PMID 33280072, 2021).
anemia (32 papers, 2012 to 2025). A reduction in the number of red blood cells, the amount of hemoglobin, and/or the volume of packed red blood cells. "In their study, it was demonstrated that caffeine attenuates hepcidin expression through the suppression of inflammation and the modulation of the IL-6/STAT3 signaling pathway, thereby presenting a compelling potential intervention for the management of anemia associated with inflammation." (PMID 40299525, 2025). "Additionally, IL-6 and other inflammatory cytokines induce the expression of hepcidin by the pathway JAK2/STAT3, causing anemia of inflammation." (PMID 38396414, 2024). "This suggests that STAT3 mutation status could be another factor for predicting or treating anemia." (PMID 32710512, 2020). "Patients in group C had a higher median age compared to group S, while group S exhibited milder anemia severity than group C. Additionally, POT1 variants were associated with the idiopathic subtype of PRCA in females, often co-occurring with STAT3 variants." (PMID 40202536, 2025). "It is one of the main contributors to hypoferremia and anemia in inflammatory and oncological disorders that are mediated by the proinflammatory cytokine IL-6/STAT3 pathway." (PMID 40299525, 2025). "Together, our findings suggest that caffeine decreases hepcidin expression via inhibiting inflammation and the activation of the IL-6/STAT3 pathway, thus presenting an attractive, potential therapeutic for the treatment of anemia of inflammation." (PMID 35888113, 2022). "Further experiments showed that maresin 1 inhibits hepcidin by reducing STAT3 phosphorylation, and thereby ameliorates anemia in this model." (PMID 30469435, 2018). "GDP (combined with ferrous sulfate) also inhibited hepcidin and improved anemia in a mouse model of inflammation, which was partly due to reduced STAT3 phosphorylation." (PMID 30469435, 2018). "Either liver-specific STAT3 knockout or IL-6 knockout mice demonstrate attenuated hepcidin induction or anemia in response to inflammatory stimuli." (PMID 29147463, 2017). "The hepatic IL-6/STAT3 signal has a role in anemia of inflammation in vivo." (PMID 23170109, 2012). "Furthermore, we found inhibitors of JAK2 or STAT3 phosphorylation could rescue anemia in rpl18 mutants." (PMID 32075953, 2020). "It has been suggested that high IL-6 plasma levels induce hypoferremia by upregulating hepatic hepcidin expression via signal transducer and activator of transcription 3 (STAT3) activation, as well as increasing plasma volume to promote anemia." (PMID 37208766, 2023). "As Il-6 increases hepcidin transcription via signal transducer and activator of transcription 3 (STAT3), this mechanism is likely responsible for low iron concentrations and contributes to the anemia observed during SCD." (PMID 35208204, 2022). "In many models of anemia of inflammation, IL-6 has been shown to be a primary driver for hepcidin induction and the SMAD1/5/8 pathway is also known to contribute, likely via activin B and STAT-3-SMAD interactions at the hepcidin promoter." (PMID 34873429, 2021). "Similarly, the STAT3 and BCL2 pathways—known for their roles in apoptosis and immune response—are modulated by compounds such as caffeic acid and melatonin, potentially explaining RG’s impact on allergy and anemia by promoting cell survival and reducing inflammation." (PMID 40699728, 2025).
Cirrhosis (32 papers, 2012 to 2025). A chronic disorder of the liver in which liver tissue becomes scarred and is partially replaced by regenerative nodules and fibrotic tissue resulting in loss of liver function. "In another Chinese study, the presence of the rs4796793C-rs2293152G-rs1053004T haplotype in signal transducer and activator of transcription 3 (STAT3) significantly increases the risk of cirrhosis." (PMID 37764954, 2023). "For instance, constitutive STAT3 activation leads to increased interleukin-6 expression, which is the main mediator of the acute phase of HB and HB-associated cirrhosis." (PMID 32024508, 2020). "A similar study has shown CCl4-induced IL-6 activation is associated with an increase in MEK5, ERK5, JAK, and STAT3 expression prior to cirrhosis." (PMID 26062544, 2015). "Our study showed that the expression of NF-κB and STAT3 in the blood samples of HCV-related cirrhosis and HCC groups with microbial dysbiosis is markedly higher than in the control participants." (PMID 41326479, 2025). "In HCV-related cirrhosis, the transcription factors NF-κB and STAT3 are chronically activated, driving persistent inflammation, liver damage, and fibrosis." (PMID 41326479, 2025). "Interleukin-22 (IL-22) facilitates the development of cirrhosis to HCC through Signal transducer and activator of transcription 3 (STAT3) signal activation." (PMID 38022519, 2023). "Although Stat3 proteins are upregulated in cirrhosis, this transcription factor appears to be functionally inactive." (PMID 36297027, 2022). "STAT3 proteins were found in abundance in the nuclei of proliferating biliary epithelial cells and hepatocytes in cirrhosis livers." (PMID 36297027, 2022). "Our data show that serum miR-122 expression level remained undetectable in most of the patients with cirrhosis (stage IV fibrosis), suggesting that the pro-survival UPR signaling increases the risk of HCC through STAT3-mediated suppression of miR-122." (PMID 31547152, 2019). "Using human liver tissue microarrays with cirrhosis, we further examined the expression levels of IL-17A, IL-17R, RORγt, STAT3 and p-STAT3 in 5 samples of normal liver tissue and in 22 samples of cirrhosis tissue by immune-histochemical staining." (PMID 28039485, 2017). "In cirrhosis, chronic stimulation by pathogen-associated and damage-associated signals sustains the TLR4–NF-κB pathway, and STAT3-mediated feedback progressively biases these cells toward tolerance, leaving T cells less responsive to subsequent checkpoint blockade." (PMID 41488615, 2025). "STAT3 proteins were detected in high concentrations in the nucleus of proliferating biliary epithelial cells and hepatocytes from the liver of patients with cirrhosis." (PMID 38751599, 2024). "We realize that the cases positive for p-STAT3 and c-Myc are few, so our results should be considered preliminary until validated by larger studies that include follow up biopsies and data on progression to both cirrhosis and HCC." (PMID 36473131, 2022). "In hepatitis B virus-related cirrhosis, IL-17 could activate STAT3 signaling pathway to induce production of type I collagen in HSCs." (PMID 32513305, 2020). "Second, we found that STAT3 activation is involved in silencing of miR-122 in the cirrhosis." (PMID 31547152, 2019). "Moreover, a positive correlation was observed between IL-17A and p-STAT3 levels in these cirrhosis tissues." (PMID 28039485, 2017). "Although differential gene expression in HCV cirrhosis has revealed a proapoptotic gene profile, a positive antiapoptotic balance through impaired Stat3 DNA-binding and Pias3 (protein inhibitor of activated Stat) upregulation has been documented in end-stage cirrhosis." (PMID 25892989, 2015). "Botanical drugs and gut microbiota target MAPK1, VEGFA, STAT3, AKT1, RELA, JUN, and ESR1 in the treatment of hepatitis B cirrhosis, and their combined use has shown promise for cirrhosis treatment." (PMID 38029250, 2023).
Cirrhosis (continued). "Although Stat3 expression and phosphorylation was not altered in HCV-mediated cirrhosis, a significantly weak Stat3 DNA-binding activity was observed in nuclear extracts from human cirrhotic liver samples with an associated upregulation of Pias3 expression." (PMID 25892989, 2015). "In addition, it is presumed that steatohepatitic HCC with cirrhosis or severe fibrosis can be well-managed along with NASH itself through targeting of the STAT-1 signaling pathway, whereas NASH-HCC without cirrhosis or fibrosis would be treated independently through the STAT-3 signaling pathway." (PMID 31456946, 2019). "On the other hand, the AUC for STAT3 and VEGF showed nonsignificant discriminators of HCC from cirrhosis in Egyptian patients." (PMID 41326479, 2025).
sarcoma (32 papers, 2007 to 2025). A usually aggressive malignant neoplasm of the soft tissue or bone. "The present study thus suggests that overexpression of STAT3 at the protein and gene level may be considered as a hallmark of sarcomas." (PMID 21575192, 2011). "IL-6/STAT3 is an essential pathway involved in the progression of metastatic sarcoma, and IL-6 production via sarcoma exosomes made mesenchymal stem cells responsible for stimulating sarcoma metastasis." (PMID 36979391, 2023). "It was recently reported that CD163-positive macrophages are also associated with both proliferation in Saos-2 cells and tumor progression in a sarcoma-bearing mouse model by IL-6-induced STAT3 activation." (PMID 32256354, 2020). "For example, dual blockage with the pan-HER inhibitor dacomitinib and the STAT3 inhibitor S3I-201 was reported to exert higher growth suppression in sarcoma cells compared to single-drug inhibition." (PMID 31422383, 2019). "Experimental evidence has demonstrated that inhibition of JAK/STAT3 signaling impairs proliferation and survival in sarcoma cell lines, supporting the notion that STAT3 is a relevant therapeutic target." (PMID 28750090, 2017). "To determine the relevance of decreased STAT3 phosphorylation in sarcoma cells, we analyzed in vitro cell viability of RMS, ES, and OS cells after treatment with LY5." (PMID 28750090, 2017). "Our data showed that LY5 has excellent target specificity for STAT3, anti-proliferative activity at nanomolar drug concentrations against several sarcoma cell lines, and promising oral bioavailability in mice and dogs." (PMID 28750090, 2017). "STAT3 is a transcription factor involved in cytokine and receptor kinase signal transduction that is aberrantly activated in a variety of sarcomas, promoting metastasis and chemotherapy resistance." (PMID 28750090, 2017). "The purpose of this body of work was to characterize the ability of LY5 to inhibit STAT3 phosphorylation in a variety of sarcoma cell lines in vitro, and evaluate the pharmacokinetic (PK) and anti-tumor properties of LY5 in vivo." (PMID 28750090, 2017). "As in sarcoma, high concentrations of Fx (50–150 μM) also inhibited STAT3 expression and phosphorylation, resulting in downregulation of cyclin B1 in gastric adenocarcinoma cells." (PMID 26264004, 2015). "In sarcoma cells, high concentrations of Fx (50–150 μM) has been shown to inhibit STAT3 expression and phosphorylation." (PMID 26264004, 2015). "Although the contribution of STAT3 to epithelial cancers and hematologic malignancies has been described in detail, little is known on the role of STAT3 dysregulation in sarcomas." (PMID 21575192, 2011). "Although the contribution of STAT3 to epithelial cancers and hematologic malignancies has been described in detail, little is known about the potential role of STAT3 dysregulation in sarcomas." (PMID 19284568, 2009). "While the function of STAT3 in carcinomas and hematopoietic neoplasia has been intensively studied, little is known about the potential role of STAT3 dysregulation in sarcomas." (PMID 19284568, 2009). "Given the low cytotoxicity of Stat3 inhibition to normal cells, targeting Stat3 signaling pathway would be a promising therapeutic strategy for sarcomas in which Stat3 is constitutively activated." (PMID 17598902, 2007). "Stat3 signaling pathway plays a role in the cell growth and survival of human sarcomas cells because our data also showed that blocking constitutive Stat3 signaling in sarcoma cells induces apoptosis and growth inhibition." (PMID 17598902, 2007). "Elevated Stat3 phosphorylation crucial for Stat3 activation was observed in most of the sarcoma cell lines we screened." (PMID 17598902, 2007). "The apoptotic effect through the blocking of Stat3 signaling in sarcoma cells was further confirmed using STA-21." (PMID 17598902, 2007). "We demonstrated that elevated levels of Stat3 phosphorylation are detected in some sarcoma tissues (15–27%)." (PMID 17598902, 2007).